IL1B (interleukin 1 beta)
Diseases named in the same sentence as IL1B in open-access papers (continued):
Sharing a sentence is not in itself a finding about the gene and the disease.
infection (continued). "High amounts of secreted IL-1β and IL-18 are detectedat 24 hr post infection under the low MOI procedure." (PMID 21533069, 2011). "NLRC4 contributes to IL-1β during the early phase of the infection and induction of pyroptosis that restricts bacterial growth." (PMID 22241982, 2011). "We found that Mtb infection significantly increased the expression of tnf-α, 2.49/3.01; ifn-γ, 2.45/4.11; il-1β, 2.76/3.43; and nos2, 2.69/5.98 at 21 and 28 days post-infection respectively (differential expression ≥1.5 fold, P<0.05)." (PMID 21364878, 2011). "Infection triggered an IL-1β, IL-8, and TNF-α response in the mammary gland, while the systemic levels of these cytokines remained unchanged." (PMID 21414189, 2011). "The mutant BMDMs or wild-type controlmacrophages were infected with Yp-YopJKIM or Yp-YopJC172A.Tissue culture supernatants were collected and analyzed by ELISA to measure thelevels of IL-1β and IL-18 present after 24 hr of infection." (PMID 21533069, 2011). "Caspase-1 was required for the processing and release of IL-1β frommacrophages under these infection conditions as shown by infecting wild-type orcasp-1-/- BMDMs with Yp-YopJKIM andisolating IL-1β from infection supernatants by immunoprecipitation." (PMID 21533069, 2011). "IL-1α and IL-1β has been known to form an important part of the inflammatory response of the body against infection." (PMID 21345237, 2011). "Both viruses tested up regulated the proinflammatory cytokine genes, IL-1β and IL-6, after infection." (PMID 21939525, 2011). "In our model of CP lung infection, IL-1β plays a critical role in orchestrating a successful host defense against infection." (PMID 21731762, 2011). "TLR3 deficient mice challenged with EMCV had decreased levels of TNFα, IL-6 and IL-1β mRNA in cardiac tissue and a corresponding reduction in inflammatory infiltrate at 3 days post infection." (PMID 21994762, 2011). "At this phase of infection before severity of disease, there was an increase in expression of various proinflammatory mediators also like Tnf-α, Il1α, Il1β, Il-12 and Ccl2/MIP-1α along with chemoattractants." (PMID 21371334, 2011). "The toxins nigericin and maitotoxin, as well as infection with Staphylococcus aureus also induce NLRP3-dependent IL-1β release." (PMID 22019906, 2011). "Production of IL-1β during the first hours of the infection was also significantly reduced in Nlrc4-/- cells." (PMID 22241982, 2011). "The inflammasome is activated in the process, giving rise to high levels of IL-1β, which increases the inflammatory response to infection." (PMID 21637850, 2011). "IL-1β is generated from cytoplasmic pro-IL-1β, which is cleaved by caspase-1 in response to infection, inflammation or immunological challenges." (PMID 21249123, 2011). "We compared the kinetics of IL-1β production following infection (in vitro and in vivo) with either the galU mutant or WT strain of FT." (PMID 21819572, 2011). "In particular, strains of the Beijing-like spoligotype induced significantly more IL-1β than the classical Beijing spoligotype after 24, 48, and 72 hours of infection (p = 0.003, p = 0.014 and p = 0.011, respectively)." (PMID 21931620, 2011). "More recently, it has been demonstrated that the AIM-2 inflammasome mediates caspase-1 activation and secretion of mature IL-1β and IL-18 during FT infection." (PMID 21819572, 2011). "MatureIL-1β was absent in supernatants isolated fromcasp-1-/- BMDMs infected withYp-YopJKIM, indicating that the processing andrelease of IL-1β during infection of wild-type macrophages withYp-YopJKIM occurred in a caspase-1-dependent manner." (PMID 21533069, 2011). "IL-1β has been known to be an important initiator of acute phase inflammatory responses to infections and more recently, found to play an critical role in establishing a Th17 response." (PMID 21731762, 2011).
infection (continued). "A previous report showed that in response to infection with Salmonella typhimurium at early time points IL-1β secretion and cell death are NLRC4 dependent." (PMID 22216309, 2011). "scSIV-LMP1 infection resulted in a significant increase in IL-1β, IL-6, IL-8, IL-10, IL-12p70 and TNF, while scSIV-LMP1-CD40 infection resulted in increase in IL-1β, IL-6, IL-8, IL-10 and TNF at various time points." (PMID 21592361, 2011). "In contrast, CC-3052 treatment resulted in decreased gene expression: tnf-α, −1.63/−1.50; ifn-γ, −1.64/−1.54; il-1β, −1.67/−1.58; and nos2, −1.68/−1.84 at 21 and 28 days post-infection respectively." (PMID 21364878, 2011). "Although essential for resistance to infections, IL-1β also exacerbates damage during chronic disease and acute tissue injuries." (PMID 22019906, 2011). "To further test the role of TLR2 in inflammasome-dependent responses, we measured the levels of IL-1β and IL-18 in macrophage supernatants following infection with F. novicida." (PMID 21698237, 2011). "The experiment performed with the microglial cells confirmed the results obtained with the enteroglial cells after the infection with M. tuberculosis and M. bovis, whereas M. paratuberculosis stimulated the production of IL-1A and IL-1B." (PMID 22151930, 2011). "Following infection with X-31 virus, the levels of IL-1β mRNA expression in Nox2−/y mouse lungs were ∼3-fold higher than that in WT lungs." (PMID 21304882, 2011). "Western blot analysis showed that compared to naive rats (0.04±0.006) and mock infected rats (0.043±0.005), IL-1β expression was significantly increased in VZV infected rats at post-infection 1 week (P1) (0.5±0.11)." (PMID 21969850, 2011). "Under the low MOI conditions the presence of 30 mM KCl in the infection mediuminhibited the secretion of IL-1β and IL-18 from macrophages infected withYp-YopJKIM, suggesting an important role for K+efflux in caspase-1 activation." (PMID 21533069, 2011). "This is likely due to the fact that WT cells rapidly die after infection while Nlrc4-/- cells remain viable and continue to synthesize and secrete IL-1β." (PMID 22241982, 2011). "Interleukin-1β (IL-1β) is a potent pro-inflammatory cytokine that is crucial for host-defence responses to infection and injury." (PMID 22019906, 2011). "Bacterial infection results in an increased release of IL-1β, which enhances phagocytic cell recruitment to infection sites." (PMID 22136135, 2011). "Pre-incubation of THP-1 cells with β-methasone, a potent anti-inflammatory corticosteroid, followed by infection with HFs resulted in a significant drop in IL-1β secretion." (PMID 20368800, 2010). "Such analysis demonstrated a 2.6-fold increase of mature IL-1β in the tails of mice infected with wild type M. marinum compared to ΔRD1 infection, suggesting that Esx-1 promotes caspase-1 activation in vivo." (PMID 20463815, 2010). "In contrast, the pro-inflammatory cytokines, TNF-α, IFN-γ, IL-1β, IL-6 and IL-12p70 only became detectable in the blood at 12 h post-infection and peaked by 72 h." (PMID 21124939, 2010). "The cell toxicity decreased by 50% at day 2 after infection in IL-1β-neutralizing antibody treated WNV-infected SK-N-SH cells when compared to WNV-infected SK-N-SH cells." (PMID 21034511, 2010). "The inhibition of IL-1β and TNF-α is a critical step in the pathogenesis of infection because mice deficient in these molecules are partially sensitive to infection with the yopH mutant." (PMID 20565713, 2010). "IL-1β and TNFα secretion was measured in the supernatants 12 hours after infection with spores, compared to 6 hour stimulation with HFs." (PMID 20368800, 2010). "We utilized western blots to measure both the pro- and cleaved forms of IL-1β from lung homogenate extracts collected one week and 20 weeks post infection." (PMID 20808838, 2010). "As IL-1β is produced in the cornea early after infection, it seems reasonable to assume that the MyD88 dependence is due to IL-1R1 signaling." (PMID 20617171, 2010).
infection (continued). "Our previous results demonstrated that IL-8 secretion induced by IL-1β was significantly decreased after infection with recombinant adenovirus expressing IL-1RII." (PMID 23554610, 2010). "Levels of IL-1β were also enhanced by infection butthe increase was more pronounced in PAFR KO than WT infected mice." (PMID 21079759, 2010). "At one week post infection only low levels of pro-IL-1β were present in the Casp-1−/− and wild type lungs." (PMID 20808838, 2010). "A549 exhibited damped oscillations after infection with H. pylori, but stable translocation after stimulation with TNFα or IL-1β." (PMID 20233427, 2010). "The time course of transient IL-12 and IL-1β expression from 8 h to 72 h after infection correlates perfectly with the critical time frame for Th1/Th2 differentiation." (PMID 20442861, 2010). "The upregulation of TLRs was paralleled by an increase of IL-1β, TNFα, and IFNγ mRNA expression, suggesting the involvement of these cytokines in the defense against infection with C. parapsilosis." (PMID 20454633, 2010). "Dectin-1 mediated activation of p-Syk, p-IκB, and translocation of NFκB to the nucleus of these cells results in production of CXCL1/KC and IL-1β within 10h of infection, and recruitment of neutrophils to the corneal stroma." (PMID 20617171, 2010). "Systemic injection of LPS induces fever and septic shock and is associated with an increase of different cytokines, including TNF-α, IL-1β and IL-6, in the blood circulation and in the brain in a pattern similar to that seen in natural infection." (PMID 21067602, 2010). "Considering the production of a vast array of proteases by practically all pathogenic microorganisms, it is to be expected that similar IL-1β activation pathways are active during other infections." (PMID 20195505, 2010). "At 20 weeks post infection pro- and cleaved IL-1β were present in both Casp-1−/− and wild type mouse lungs with more found in the former." (PMID 20808838, 2010). "First, we examined the daily regulation of cytokines mobilized following insult to the host by injury or infection, including TNFά, IL-1β, IL-6 and IL-18." (PMID 21194436, 2010). "TUNEL-positive cells were abundant in WNV-infected cells at day 2 after infection, which reduced significantly (p <0.05) in the presence of anti-IL-1β or -TNF-α." (PMID 21034511, 2010). "Mice in which lethal toxin activates the Nlrp1b inflammasome show an IL-1β response and increased neutrophil recruitment leading to increased resistance to infection." (PMID 21170303, 2010). "One very interesting phenomenon has recently been reported during infection with C. albicans, in which a fungus-derived protease can lead to processing and activation of host-derived pro-IL-1β and thus activation of the immune system." (PMID 20195505, 2010). "Proinflammatory cytokines IL-1β and TNFα were augmented by the C. parapsilosis-infected oral epithelial cells at early and late infection periods, while IFNγ was involved only at early defense phase, as previously reported with C. albicans." (PMID 20454633, 2010). "Proinflammatory cytokines CXCL8 and CXCL5 are chemoattractants for neutophils, IL-1α and IL-1β are important proinflammatory cytokines and would be expected to be increased early in infection." (PMID 22331987, 2010). "IL-1β levels increased during the logarithmic growth phase of infection and were still high during the persistence phase of infection." (PMID 20808838, 2010). "Resistance to infection required the actions of both caspase-1 and IL-1β as Nlrp1bS/S mice deleted of caspase-1 or the IL-1 receptor, or treated with the Il-1 receptor antagonist anakinra, were sensitized to infection." (PMID 21170303, 2010). "C57BL/6NTac Nlrp1bS/S mice produced significantly higher levels of IL-1β than their C57BL/6NTac Nlrp1bR/R counterparts very early in infection, when toxin production is relatively low." (PMID 21170303, 2010).
infection (continued). "Briefly, mice were treated with monoclonal antibodies to TNF-α, IL-1β, TNF-α+IL-1β, or the appropriate control IgG one day prior to infection and then every third day for the course of the infection." (PMID 20565713, 2010). "In the absence of YopH, the host responds to the presence of Y. pestis with an early pro-inflammatory response, namely, an increase in TNF-α and IL-1β in the BALF at 24 h post-infection, which diminishes in magnitude by 48 h post-infection." (PMID 20565713, 2010). "We measured the activation of caspase-1 after infection of macrophages with M. leprae because the maturation and secretion of IL-1β is dependent on the activation of caspase-1." (PMID 20671924, 2010). "In conclusion, IL-1β/IL-18 processing during infection is a complex process in which the inflammasomes are only one of several activation mechanisms." (PMID 20195505, 2010). "Release of cytokines such as IL-1β and IL-18 after LPS or infection with non-invasive bacteria such as E. coli was significantly increased in Atg16L1-null macrophages." (PMID 20107532, 2009). "Intriguingly, IL-1β release after infection with invasive bacteria such as Salmonella typhimurium was not increased in Atg16L1-null macrophages." (PMID 20107532, 2009). "It is possible that early activation of NLRP3 and IL-1β production results in the infiltration of neutrophils and monocytes to the sites of infection where these cells continue to secrete cytokines resulting in a “cytokine storm”." (PMID 19798428, 2009). "The peak expression levels of MIP-2, KC, and IL-1β occurred at one day post-infection, and the mRNA expression levels gradually decreased later." (PMID 19590756, 2009). "Next, to examine the role of IL-1β and IL-18 receptors during L. pneumophila infection, corresponding antibodies to IL-1 receptor and IL-18 receptor were added during infection." (PMID 19343209, 2009). "Tumor necrosis factor (TNF)-α is another prototypical pro-inflammatory cytokine that is induced in concert with IL-1β in response to infection, injury, and immunological challenge." (PMID 19325908, 2009). "Immune response-associated genes, with altered expression in virulent strain infection, were selected for further investigation: Tlr2, Tlr4, Tlr13, Myd88, Il1b, Il6, dectin-2 and Cxcl12." (PMID 19845042, 2009). "The R. equi model of infection has revealed galectin-3's ability to exert a regulatory role in innate immunity by diminishing macrophage IL-1β production." (PMID 19229338, 2009). "After treatment with IL-1β polyclonal antibody, the inflammatory responses and pathological scores were significantly reduced one and three days post-infection (p<0.01)." (PMID 19590756, 2009). "Although IL-18 and IL-1β production in response to LPS and infection varied markedly between donors; Mφ1 of all donors produced both IL-18 and IL-1β in response to these stimulations." (PMID 20027291, 2009). "We further demonstrate that inhibition of the inflammasome with a caspase-1 inhibitor did not prevent the induction of NF-κB regulated cytokines following infection with vMyxM013-KO virus, but did block the activation of IL-1β." (PMID 19851467, 2009). "In adult mice, IL-1β (pro-inflammatory cytokine) concentrations peaked at day 5 post-infection, but steadily increased in aged mice." (PMID 19922665, 2009). "Interleukin (IL)-1β is a pro-inflammatory cytokine that functions as a critical regulator of host defense in response to infection and injury." (PMID 19325908, 2009). "In the vaccination model used here, however, there is a significant dampening of the infection-induced increase in IL-1β, TNF, IL-6 and iNOS, especially observable at peak parasitaemia." (PMID 19341445, 2009). "There is some controversy about the relevance of the NF-κB and AP-1 binding sites in the promotor of hBD-2 for full induction of hBD-2 expression after treatment with IL-1β or infection with microbiota." (PMID 19523197, 2009).
infection (continued). "When experimental mice were subconjunctivally injected with IL-1β polyclonal antibodies, the corneal inflammatory responses were significantly reduced at an early stage (one to three days post-infection)." (PMID 19590756, 2009). "The serum levels of TNF-α, IL-1β and IL-6 augmented after challenge, reaching the maximum values between 24 h and 48 h post-infection." (PMID 19835595, 2009). "The supernatants were collected at different time points after infection and tested for secreted IL-1β and TNF by ELISA." (PMID 19851467, 2009). "The two neutrophil chemoattractant proteins MIP-2 and KC are induced by both TNF-α and IL-1β in response to inflammatory stimuli such as silica or infection." (PMID 19901996, 2009). "IL1β, which increased 4 fold, is a proinflammatory cytokine whose expression is triggered by tissue injury or infection." (PMID 18615202, 2008). "Although in general the pulmonary concentrations of these mediators were lower in TLR2 KO mice, the differences with WT mice were statistically significant only for KC (P < 0.005 at 24 and 48 h post infection) and IL-1β (P < 0.05 at 48 h)." (PMID 17711480, 2008). "Corneal injury results in the upregulation of IL-1β, and infection further increases its expression." (PMID 18843377, 2008). "Classically IL-1β is stimulated early during an infection or stimulation of cells, with 3–6 h being an optimal time for IL-1β to be expressed and then to induce down stream genes." (PMID 17555569, 2007). "It is possible that the secretion of IL-1β, IL-6, IL-10, and TNFα in the choriodecidua region after infection with Escherichia coli would favor their trans-membranal translocation to the amnion and thereby exert their effect on the whole membrane." (PMID 18078521, 2007). "IL-1β, which was highly induced at later stages of infection, was initially repressed on the first day after infection." (PMID 17725815, 2007). "IL-1β is a pro inflammatory cytokine directly stimulating the innate immune system and during later stages of infection has major roles in the activation of T and B cells." (PMID 17555569, 2007). "Transcripts encoding the proinflammatory cytokines IL-1β, IL-6, IL-8, and tumor necrosis factor (TNF)-α were markedly increased in late-stage animals (average fold increase at day 5 after infection: IL-1β, 3.9; IL-6, 4.3; IL-8, 11.3; and TNF-α, 5.2)." (PMID 17725815, 2007). "Microglia appear to be the earliest and major source of IL-1 after CNS injury, infection or inflammation, and they express caspase-1, the enzyme responsible for converting pro-IL-1β to its active form." (PMID 16808851, 2006). "Only modest increases of expression of the pro-inflammatory cytokine IL-1β were found following infection, though significantly greater in infected birds at two weeks post infection (P = 0.02)." (PMID 16221297, 2005). "Amniotic fluid was analyzed for the presence of microorganisms andendotoxin to confirm intraamniotic infection; cytokines interleukin (IL)-1β, IL-6, and IL-8 werealso assayed." (PMID 18475321, 1993). "In some cases, IL-1β levels may increase in the early stage of infection; however, as the condition progresses, their changes can be influenced by disease progression, immune system regulation, and the effects of medications." (PMID 41313182, 2026). "Deletion of asfR and tmRNA results in lower secretion of cytokine IL-1β during mouse infection." (PMID 41367294, 2026). "During infection or injury, IL-1β is released by both human and mouse macrophages." (PMID 42282704, 2026). "pylori infection-induced increase of cytokines (IL-6, IL-1β) in GES-1 cells." (PMID 42112454, 2026). "In addition to suppressing cell death, infection with mT3Sf::OspF also prevented IL-1β processing as compared to mT3Sf::empty." (PMID 41533441, 2026).